PDGFRA (platelet derived growth factor receptor alpha)
Diseases named in the same sentence as PDGFRA in open-access papers (continued):
Sharing a sentence is not in itself a finding about the gene and the disease.
glioblastoma (continued). "Among the molecular biomarkers evaluated, BRAF, H3F3A-K27M, IDH1 and PDGFRA demonstrated prognostic relevance in young adult glioblastomas." (PMID 26452024, 2016). "We and others recently demonstrated that inhibition of either PDGFRα or PDGFRβ signaling induced apoptosis in glioblastoma stem cells." (PMID 27344175, 2016). "Similar changes in the apparent levels of HSP90, GRP78 and HSP70 were also obtained using immuno-fluorescence in the primary human glioblastoma isolates GBM5 (PDGFRα+) and GBM12 (mutant active full length ERBB1)." (PMID 26887051, 2016). "Within this aggressive subset of glioblastoma, tumors with positive PDGFRA immunohistochemical expression exhibited a significantly shorter survival (median 2.5 months) than tumors with negative expression (median 11.7 months) (p = 0.03)." (PMID 26452024, 2016). "In the context of a PDGFRα mutant occurring in glioblastoma, aberrant intracellular localisation was detected." (PMID 25880691, 2015). "Our results collectively support a key role of EGFR and PDGFRα signaling in survival of Glioblastoma cancer stem cells." (PMID 25380967, 2014). "Amplification of the 4q12 region encompassing the PDGFRA gene was seen only in anaplastic astrocytomas (3/36; 8%) and glioblastomas (14/225; 6%)." (PMID 24952577, 2014). "Recombinant gB protein and the whole virus enhanced invasion of primary glioblastoma cells into Matrigel and rat brain slices, and this effect was specifically inhibited by neutralizing antibodies to either gB or PDGFRα." (PMID 24658280, 2014). "The first fusion gene found in glioblastoma was the rearrangement located at an amplified region at chromosome 4q12, resulting in the fusing of the kinase domain of PDGFRA with the regulatory domains of KDR (VEGFR2)." (PMID 24548782, 2014). "PDGFRA mRNA overexpression was detected in the low- and high-grade astrocytomas and PDGFRA amplification is typical in the signaling pathway that results in the development of secondary glioblastoma." (PMID 25364409, 2014). "Of most interest was the use of the iCNA algorithm to identify potential novel fusion genes, as was demonstrated in adult glioblastoma with the identification of the KDR:PDGFRA fusion, which we also found in a case of pHGG." (PMID 24548782, 2014). "Of note, only PDGFRA overexpression conferred a worse overall survival in glioblastoma patients (p = 0.028, log-rank test)." (PMID 23990986, 2013). "DBA also identified DNA copy-number transitions within platelet-derived growth factor receptor alpha (PDGFRA) in glioblastoma (SNB19) and chronic eosinophilic leukemia (EOL-1)." (PMID 23637631, 2013). "In glioblastoma, amplification/overexpression of PDGFRA has provided the rationale for clinical studies, with disappointing results to date." (PMID 23990986, 2013). "A younger age at diagnosis and better clinical outcome in glioblastoma patients is only seen when PDGFRA and KIT are co-amplified." (PMID 23990986, 2013). "Important for our studies, PDGFRα activation affects both dynamin-2 that interacts with activated PDGFRα at the advancing edges of motile glioblastoma cells and cortical actin cytoskeleton leading to marked membrane ruffling." (PMID 23028311, 2012). "Only 16% of glioblastomas showed PDGFRA amplification, which suggested that other mechanisms were responsible for PDGFRA overexpression in the majority of tumors." (PMID 22509804, 2012). "Dock1 (DOCK180), a GEF for Rac, becomes tyrosine phosphorylated by Src downstream of PDGFRα activation in glioblastoma cells." (PMID 23152932, 2012).
glioblastoma (continued). "PDGFRα, a well known oncogene, displays increased copy numbers in different tumor entities including glioblastoma." (PMID 20686603, 2010). "Glioblastoma datasets from The Cancer Genome Atlas were analyzed for alterations in EGFR, PDGFRA and NF1 and the possible association of mutations in these genes with transcriptomally-defined subclasses." (PMID 19915670, 2009). "When the presence or absence of PDGFA/PDGFRA overexpression (+++) was defined according to histological type, a trend for PDGFA and PDGFRA coexpression in glioblastomas was found (P=0.069)." (PMID 19707201, 2009). "Clinical trials evaluating the efficacy of anti-PDGFRA drugs in patients with glioblastomas are ongoing." (PMID 19707201, 2009). "PDGFRA amplification has been reported to be more common in diffuse hemispheric gliomas, H3 G34-mutant with glioblastoma-like histology versus tumors with primitive neuronal/neuroectodermal tumor-like features, while CCND2 amplification showed the opposite trend, but this was not seen in our cohort." (PMID 39842935, 2025). "Furthermore, expression of several genes associated with glioblastoma (STAT3, PDGFRA, MET, and NF1) and neuroblastoma (GATA3, ISL1, LMO1, and LIN28B) progression was downregulated at the transcriptional level in differentiated cells." (PMID 39859209, 2025). "While PDGFRα, which is the second most amplified receptor in glioblastoma after EGFR, is primarily upregulated in the proneural subtype, PDGFRβ is preferentially expressed in glioma stem cells (GSCs), where it regulates the level of stem cell markers, like SOX2." (PMID 37762559, 2023). "GRB14 and PDGFRα exhibited high expression levels in glioblastoma tissues and cell lines." (PMID 33867829, 2021). "Amplification of receptor kinases such as EGFR and PDGFRA (platelet-derived growth factor receptor alpha) are relevant to the prognosis of glioblastoma, and both may coexist in a tumor." (PMID 30374421, 2018). "Amplification of PDGFRα is a common alteration in glioblastoma." (PMID 30082792, 2018). "The results implied that CYTOR and MIAT may be associated with amplification of PDGFRA and IDH1 mutations, HAR1A may be related with neuron markers in glioblastomas." (PMID 29108264, 2017). "Distinct genomic aberrations including PDGFRA alterations and hotspot mutations in histone 3.3 (H3F3A) at codons 27 (K27) and 34 (G34) as well as histone 3.1 (HIST1H3B) at codon 27 (K27) were frequently found in glioblastomas in children." (PMID 26452024, 2016). "In addition, The Cancer Genome Atlas (TCGA) classified glioblastomas on the basis of PDGFRA, IDH1, EGFR, and NF1 abnormalities in classical, mesenchymal, proneural, and neural subtypes, and these four subgroups seemed to present distinct outcomes." (PMID 26637806, 2016). "We show that human glioblastomas endogenously express gB and PDGFRα, often in the same cells, which suggests that this growth promoting signaling pathway may indeed contribute to the invasive phenotype of HCMV positive GBMs." (PMID 24658280, 2014). "PDGFRA and KIT too, may be expressed in the glioblastoma-associated vasculature, although they have been less extensively studied." (PMID 23990986, 2013). "Also, allelic losses on 19q and 13q, promoter hypermethylation of the RB1 gene, and overexpression of PDGFRA are more common in secondary glioblastomas." (PMID 19333441, 2009). "Furthermore, single-cell RNA sequencing (scRNA-seq) has provided crucial insights into the transcriptomic heterogeneity of glioblastomas, identifying key genes such as PDGFA, PDGFRA, CREB1, and PLAT that are strongly linked to tumor progression and patient survival." (PMID 40332008, 2025).
glioblastoma (continued). "The abnormality of PDGFRA could characterize proneural subtype in glioblastoma." (PMID 37491836, 2023). "Well-known somatic drivers of glioblastoma (GBM) heterogeneity, including PDGFRA, IDH1, EGFR, and NF1, have altered how we treat patients, diagnose disease, and design clinical trials." (PMID 37252795, 2023). "– a mutation in PDGFRA is predominantly found insecondary but not primary glioblastomas." (PMID 31413876, 2019). "Here, we found that several of the most frequently mutated genes in glioblastoma including: EGFR, PTEN, NF1, PIK3R1, RB1, PDGFRA and QKI possessed high 5 hmC levels across intronic regions and further loss of 5 hmC in tumours may reflect a loss of genome integrity." (PMID 27886174, 2016). "HHT treatment of GBM can inactivate STAT3 signaling by inhibiting PDGFRα phosphorylation and PDGFRα/Ras homolog family member A (RhoA)/Rho-associated coiled-coil-containing protein kinase (ROCK) axis to reduce glioblastoma cell proliferation, cytoskeletal remodeling, and migration." (PMID 39949739, 2025). "In this study, we identify and functionally characterize a novel amplified fusion, MDM2 (exon 1)::PDGFRA (exon 8), mediating resistance to cetuximab in an EGFR-amplified glioblastoma." (PMID 40819143, 2025). "In glioblastoma, alterations in CDKN2A/B and PDGFRA were significantly enriched in patients ≥65 years old while there was a depletion of these alterations in patients between 40 and 64 years old." (PMID 39164213, 2025). "In chromosomal region 4q12, PDGFRA, KIT, and KDR genes are localized, which play critical roles in development of glioblastoma." (PMID 39684714, 2024). "In glioblastoma, most RTK driver alterations were CN gains/amplifications, accounted for by EGFR, PDGFRA, and to a lesser extent, MET." (PMID 38254850, 2024). "Members of the receptor tyrosine kinase gene family including EGFR, MET, PDGFRA, and FGFR3 have been known to be heavily involved in the initiation and progression of glioblastoma." (PMID 39087020, 2024). "The G5/PDGFRA and G6/Multi-RTK are minor molecular subgroups, composing less than one fifth of all glioblastoma cases." (PMID 38254850, 2024). "The four RTK subgroups, G1/EGFR, G2/FGFR3, G5/PDGFRA and G6/Multi-RTK, totaled over 50% of the cases, underscoring the importance of RTK signaling for glioblastoma pathogenesis." (PMID 38254850, 2024). "In glioblastoma cells, CCN3 increased cell proliferation via a platelet-derived growth factor receptor A (PDGFRα)-dependent mechanism." (PMID 36737605, 2023). "Amplification of Platelet-Derived Growth Factor Receptor Alpha (PDGFRA), EGFR, and MET genes is also observed in IDH-wild-type glioblastomas." (PMID 35989351, 2022). "A study reported that the molecular classification of glioblastoma involving IDH1, PDGFRA, EGFR, and NF1 substantially benefits the prediction of prognosis and response to therapy in glioblastoma patients." (PMID 36090889, 2022). "Enhancement or alterations of PDGFRA, EGFR, insulin-like growth factor receptor (IGFR-1), and basic fibroblast growth factor receptor 1 (FGFR1) accounts for 80% of the primary glioblastoma." (PMID 36185622, 2022). "Two of the ephrin class RTKs, EPHA3, and EPHB2, also showed overexpression in scattered cases across the glioblastoma subgroups but more prominently in the Multi-RTK and PDGFRA subgroups, respectively." (PMID 34572759, 2021).
glioblastoma (continued). "The combined NF1, RAF, and RTK alterations from EGFR, PDGFRA, FGFR3, and Multi-RTK subgroups that activate the ERK/MAPK signaling pathway accounted for 85% of the glioblastoma IDH-wild-type cases." (PMID 34572759, 2021). "The efforts for molecularly classifying glioblastoma have been recently reviewed and are based on a bioinformatics study categorizing in three different clusters the tumors with EGFR, NF1, and PDGFRA/IDH genetic alterations." (PMID 34572759, 2021). "The integrated genomic and transcriptomic analysis of the tumors showed EGFR, PDGFRA, FGFR3, NF1, and BRAF/RAF1 mutually exclusive alterations within the glioblastoma IDH-wild-type category." (PMID 34572759, 2021). "The RTK subgroups G1/EGFR, G2/FGFR3, G5/PDGFRA, and G6/Multi-RTK accounted for roughly two-thirds of the glioblastoma IDH-wild-type cases, indicating a major role of RTKs in the pathogenesis of glioblastoma." (PMID 34572759, 2021). "The ldrEXOs-derived circ-METRN enhanced the glioblastoma progression and radioresistance via miR-4709-3p/GRB14/PDGFRα pathway." (PMID 33867829, 2021). "These glioblastoma molecular subgroups are classified as G1/EGFR, G2/FGFR3, G3/NF1, G4/RAF, G5/PDGFRA, G6/Multi-RTK, and G7/Other." (PMID 34572759, 2021). "We observed several recurrent chromosomal aberrations that are often dysregulated in glioblastoma progression in both cohorts including amplification of chromosome 7 and 4, harboring EGFR and PDGFRA respectively." (PMID 32794373, 2020). "This is an antiproliferative miRNA that interferes with biological pathways that target genes involved in glioblastoma pathogenesis, including EGFR and platelet-derived growth factor receptor alpha (PDGFRA), E2F3a, and WEE1." (PMID 31013819, 2019). "According to the Cancer Genome Atlas (TCGA) genetic screening, 86% of human glioblastoma samples harbor at least one genetic alteration event in the core RTK pathways, and EGFR, PDGFRα, and MET are most commonly amplified RTKs in glioblastomas." (PMID 31245283, 2019). "Genes known to be the most frequently amplified in glioblastoma, EGFR, CDK4, PDGFRA, MDM2, MDM4 are all found to be involved in tumorigenesis of a variety of cancers and are members of several signaling pathways notoriously involved in cancer." (PMID 30871102, 2019). "The analysis of glioblastomas bearing both EGFR and PDGFRA amplifications provided evidence for a consistent degree of heterogeneity at the level of the cell populations of a single tumor." (PMID 30279357, 2018). "RTK genes are frequently altered in glioblastomas; in fact, at least one RTK is altered in 65–75% of glioblastomas (EGFR (50–58%), PDGFRA (12–15%), MET (2–3%), and FGFR2/3 (3%))." (PMID 30279357, 2018). "We analysed gene expression of the PDGF system (PDGFA, PDGFB, PDGFC, PDGFD, PDGFRA, PDGFRB) in 36 GBMs studied on Ivy Glioblastoma Atlas Project." (PMID 29127351, 2017). "Analysis of TCGA glioblastoma data demonstrates that at least 4% (16/434) of tumors harbor explicit co-amplification of EGFR and PDGFRA, however a much larger fraction of tumors show co-expression of the corresponding mRNAs at comparable levels." (PMID 28831081, 2017). "High-level focal amplifications of EGFR, PDGFRA, and CDK4 were detected in affected glioblastoma samples." (PMID 28638988, 2017). "Our work aimed to assess the role of PDGFRα signaling in self-renewal, differentiation, invasion and EMT phenotype in glioblastoma CSC through the knockdown of PDGFRα expression." (PMID 27344175, 2016). "In glioblastomas (GBM), the most common alterations were gene amplifications (PDGFRA, KIT, KDR, EGFR, and MET) and deletions (CDKN2A and PTEN)." (PMID 27172220, 2016). "Because of the critical role of PKCα in promoting EMT phenotype and malignant progression of glioblastoma cells, we hypothesized that PKCα could regulate stemness of GBM CSC downstream of the PDGFRα signaling cascade." (PMID 27344175, 2016).
glioblastoma (continued). "Those genes include EGFR, PDGFRA, FGFR3, PIK3CA, MDM4, CDKN2A/B, PTEN and are all members of the core alterated pathways in glioblastoma controlling key phenotypes such as proliferation, apoptosis and angiogenesis." (PMID 25679508, 2015). "Our smMIP technique detected amplification of PDGFRA, KIT and EGFR within tumor BI05, an IDH1-wild type glioblastoma." (PMID 25608559, 2014). "For example, single gene amplification of KIT on chromosome 4 can occur in testicular tumors, yet larger amplicons containing KIT, PDGFRA, and KDR are amplified in glioblastoma." (PMID 24874471, 2014). "Glioblastoma cells express all PDGF ligands and their specific receptors, PDGFRA (alpha) and B (beta)." (PMID 23998913, 2013). "Five moderate to high-level amplified genes in glioblastomas identified in this study, EGFR, PDGFRA, CDK4, MDM2 and CYP27B1, have also been previously reported, sometimes with co-amplification." (PMID 22691727, 2012). "In the previous report, the tyrosine kinase inhibitor imantinib methanesulfonate (Gleevec) substantially inhibited PDGFRα-mediated phosphorylation of Akt and HCMV IE expression in human embryonic lung (HEL) cells and U87 glioblastoma cells." (PMID 23028311, 2012). "Relationships between molecular alterations also emerged: notably, EGFR alterations were positively correlated with both CDKN2A/B and PDGFRA alterations in IDH1/2-mutant astrocytoma, reflecting the cooccurrence of canonical glioblastoma molecular alterations in these tumors." (PMID 39164213, 2025). "Other drugs such as chlorpromazine, echinomycin, fenofibrate, and R50922/R59949 inhibit glioblastoma growth via several mechanisms, including the blockade of dopamine signaling, interference with the HIF1α-PDGFD/PDGFRα-AKT pathway, and the induction of apoptosis." (PMID 38893207, 2024). "Moreover, the analysis of DNA copy number variation of 543 glioblastoma samples shed light on some common amplification events on chromosome 7 (EGFR, MET, CDK6), chromosome 12 (CDK4 and MDM2), and chromosome 4 (PDGFRA)." (PMID 39148319, 2024). "Here, the mutation c.1403A > G in exon 10 of the platelet-derived growth factor receptor-alpha (PDGFRA) gene, a VUS found in adult glioblastoma multiforme (GBM), was introduced in human embryonal kidney 293 T (HEK293T) cells using genome editing to investigate its potential oncogenic functions." (PMID 35075231, 2022). "Imatinib and other PDGFRα inhibitors have been used in a wide variety of model systems and clinical studies (e.g., SCI, stroke, MS, retinal neovascularization, fibrosis, CML, GI stromal tumors, glioblastoma) to address effects on the immune response." (PMID 35528149, 2022). "Taken together, low-dose radiation-induced exosomal circ-METRN may exert its positive regulatory functions in glioblastoma progression and radioresistance via miR-4709-3p/GRB14/PDGFRα pathway." (PMID 33867829, 2021). "In addition to these frequent abnormalities of EGFR and PDGFRA, more rarely abnormalities of another RTK, FGFR, have been described in approximately 3% of glioblastoma patients." (PMID 30279357, 2018).